SLC11A1 (solute carrier family 11 member 1)
Diseases named in the same sentence as SLC11A1 in open-access papers (continued):
Sharing a sentence is not in itself a finding about the gene and the disease.
infection (continued). "SLC11A1 functions as a divalent transition metal transporter involved in host resistance to infection with Mycobacterium tuberculosis and M. leprae, and also is associated with some inflammatory diseases." (PMID 31069175, 2019). "By contrast, following intranasal infection, the Slc11a1+ and Slc11a1+Tlr2/4/9−/− mice accumulate very little cytokine in either in serum or lung after intranasal infection." (PMID 28360906, 2017). "Slc11a1 (also known as Nramp1) has long been known to influence the course of infection with S. Typhimurium and certain species of Mycobacterium and Leishmania." (PMID 28443246, 2017). "Strikingly, the Slc11a1+ BMDM made significantly more ROS in response to LVS starting at 20 min after infection and increasing throughout the assay." (PMID 28360906, 2017). "One hour after infection there were slightly fewer LVS in Slc11a1+ than B6 BMDM at both 100 and 1 MOI." (PMID 28360906, 2017). "To examine the impact of functional Slc11a1 expression on the innate immune response to LVS infection, we measured cytokine production in both the serum and lung homogenates of Ft infected mice." (PMID 28360906, 2017). "Combined with our data it seems that functional Slc11a1 expression in a B6 background in beneficial for LVS infection, whereas with the interactions from chromosome 2 Slc11a1 expression can be detrimental." (PMID 28360906, 2017). "The natural resistance macrophage protein 1 (Nramp1 or Slc11a1) has been characterized as a late phagosomal protein conferring resistance to infection with Salmonella, Mycobacteria, and Leishmania." (PMID 25076907, 2014). "Mice with functional SLC11A1 mount primarily a Th1 response to vaccination with the parasite metalloprotease Gp63 and display decreased skin lesions during a challenge infection with L. major." (PMID 24367768, 2013). "In mice, early control of bacterial replication following infection with S. typhimurium is controlled by slc11a1." (PMID 17378896, 2007). "The AMP repertoire is also dependent on the mouse genetic background and could explain that - in addition to Nramp1/Slc11a1 status - some mouse strains are more resistant to STm infection." (PMID 35733975, 2022). "We therefore examined the effect of Slc11a1 expression on footpad infection." (PMID 28360906, 2017). "Because we found so little cytokine in Slc11a1+ mice we hypothesized the cellular milieu in the lung would differ after infection." (PMID 28360906, 2017). "In our hands, all Slc11a1+ mice showed marked resistance to intranasal LVS infections." (PMID 28360906, 2017). "Francisella is sensitive to iron starvation when cells are treated with bafilomycin A to limit Francisella escape into the cytosol, sequestration of iron by Slc11a1 may play a role in the resistance to LVS infection." (PMID 28360906, 2017). "Since Slc11a1 is preferentially expressed in macrophages and alveolar macrophages, we speculated that the impact of Slc11a1 might differ depending on the route of infection." (PMID 28360906, 2017). "NRAMP1 (SLC11A1) is a professional phagocyte membrane importer of divalent metals that contributes to iron recycling at homeostasis and to nutritional immunity against infection." (PMID 28467369, 2017). "These differential effects depending on cell type may help explain the differences seen in Slc11a1+ mice depending on the route of infection." (PMID 28360906, 2017). "Slc11a1 plays an important role in innate immunity, preventing bacterial growth in the early stages of infection; it may either contribute to bactericidal activities of macrophages or be involved in more general processes of macrophage activation." (PMID 25874773, 2015). "An important host factor that controls bacterial infection is the natural resistance-associated macrophage protein 1 (NRAMP1, also known as SLC11A1) and several research groups determined the contribution of the SLC11A1 locus to severity of infection within animal models." (PMID 24106689, 2013).
infection (continued). "The survival rate of young chicks derived from a backcross between lines W1 and C and infected intra-muscularly one day post-hatch with S. Typhimurium was linked to SLC11A1 and TLR4, which, together, explained up to 33% of the differential resistance to infection." (PMID 20429884, 2010). "Thus, the potential role of SLC11A1 in later stages of the infection was demonstrated, firstly in mice inoculated with S. Enteritidis at 8-10 weeks with spleen bacterial counts, 42 days post-infection." (PMID 20429884, 2010). "Studies determining susceptibility for mycobacterial infections have identified host genetic factors that increase risk for these infections; examples are polymorphisms in the major histocompatibility complex, TLR, vitamin D receptor genes, genes encoding IFN-gamma signaling components and SLC11A1." (PMID 32033287, 2020). "As for the in vivo experimental infection, it has yet to be determined whether Slc11a2-β is functioning as SLC11A1 or SLC11A2, but since both forms are known to be required for an efficient erythrophagocytosis and iron recycling in macrophages, it is likely that it is performing both functions." (PMID 21501491, 2011). "Our study was not sufficiently powered to look for interaction between the CXCR1 and SLC11A1 in this study, and further work will be needed to determine whether the association at SLC11A1 relates to its role in PMN, macrophages or dendritic cells at the site of infection." (PMID 20089160, 2010). "However Slc11a1 expression after infection may be correlated with macrophage numbers and the control of oxidative stress rather than iron storage." (PMID 19365556, 2009). "It would be interesting to study further if the SLC11A1 phosphorylation is also required for SLC11A1-modulated NO production in response to other stimuli such as IFN-γ, and intracellular infection." (PMID 29723216, 2018). "They reported that A/J mice, which are Slc11a1+, are more sensitive to LVS infection as compared to B6 mice." (PMID 28360906, 2017). "A clear difference in expression of iron regulatory genes was observed with a consistent and significant down-regulation of FTH1, SLC11A1, SLC11A2, HMOX1 and TFRC in animals controlling the infection." (PMID 24505407, 2014). "The genomic regions carrying the candidate genes TLR4 and SLC11A1, the Major Histocompatibility Complex (MHC) and the QTL SAL1, identified using several infection models, are interesting candidates for more in-depth studies." (PMID 20429884, 2010). "Conversely, CpG sites related to Slc11a1, Havcr2, Ccl11, Ccl12, Sirt1, Ifng, Ccl3, Ror2, and Trem2 maintained lower methylation levels throughout the infection compared to noninfected samples." (PMID 40170749, 2025). "By 16 h, LVS was still undetectable in Slc11a1+ BMDM at an MOI of 1, at the MOI of 100 there was a 100-fold decrease in bacteria recovered compared to the B6 BMDM and 10-fold compared to the Slc11a1+ 1 h after infection." (PMID 28360906, 2017). "This resistance to even very high-dose challenges of LVS, even in the absence of TLR2, highlights the strong effect functional Slc11a1 has the outcome of LVS infection." (PMID 28360906, 2017). "Strikingly in Slc11a1+ mice, we detected no increased cellularity compared to naïve mice at either 3 or 5 days post-infection." (PMID 28360906, 2017). "Functional Slc11a1 can not only overcome a lack of TLR2, but Slc11a1+Tlr2−/− mice are more resistant to intranasal LVS infection than B6 mice." (PMID 28360906, 2017). "Agents that activate macrophage together with host SLC11A1 alleles will exert different effects on SLC11A1 function, but how SLC11A1 functions help determine the outcome of infection by modulating the production of these cytokines in not known." (PMID 17378896, 2007). "Thus, the resistance to infection is not due to increased recruitment of innate cells, but rather a cell intrinsic property of the resident infected cells of Slc11a1+ mice." (PMID 28360906, 2017).
infection (continued). "Thus Slc11a1 is a critical player in murine resistance to pulmonary Francisella infection, but not footpad infection." (PMID 28360906, 2017). "Slc11a1+ mice had little to no detectable bacteria by day 3 post-infection." (PMID 28360906, 2017). "Thus, constitutive SLC11A1 expression may not differ markedly between phenotypic groups, but the allelic context could still affect inducible expression during infection or cytokine stimulation, a hypothesis that merits further investigation using MAP-infected macrophages." (PMID 41305387, 2025). "The results showed that SNPs rs109915208, rs110514940, and rs110905610 on SLC11A1, c.480G>A and c.625C>A on PGLYRP1, and c.2021C>T on TLR4 were monomorphic in both seropositive and seronegative cattle and therefore had no influence on the infection outcome." (PMID 33644146, 2021). "In addition to maintaining weight, we were not able to recover any viable LVS from Slc11a1+ mice (LOD, 50 CFU) in any of the organs tested at day 3 post-infection." (PMID 28360906, 2017). "Loss of vaccine-mediated protection during malaria parasite infection was independent of Slc11a1 (Nramp1) genotype and route of S. Typhimurium infection, as we observed the same effect in both C57BL/6 Slc11a1+/+ mice with i.v. infection routes and in CBA mice with intragastric (i.g.)routes." (PMID 26366739, 2015).
bacterial infection (23 papers, 2008 to 2025). "The Slc11a1 gene encodes a Fe+ and Mn+ transporter protein in leukocyte populations (especially in macrophages and monocytes) that is important in fighting bacterial infections." (PMID 36792680, 2023). "This is worth mentioning because one of the best-known genetic factors influencing susceptibility to bacterial infection is a solute carrier transporter, Slc11a1 (also known as Nramp1)." (PMID 24594938, 2014). "Specifically Slc11a1 (i.e. Nramp), which was significantly upregulated in F4/80low MΦ by bacterial infection, was virtually unchanged in tissue resident derived MΦ." (PMID 28334040, 2017). "A genetic basis for differences in resistance to Salmonella has also been shown with SLC11A1 (NRAMP1), the seminal example of a gene with genetic variants dramatically affecting resistance to bacterial infection." (PMID 24912583, 2014). "It is known that SvEv/129, but not C57/B6, mice are naturally deficient in the Slc11a1 (Nramp1) gene expressed in macrophages that functions to protect mice from certain intracellular bacterial infections." (PMID 25798870, 2015). "Previous studies on the innate response of macrophages during intracellular bacterial infection suggested that SLC11A1-mediated deprivation of divalent cations might change the phagosomal microenvironment that impairs the pathogenesis of intracellular pathogens." (PMID 19768110, 2009). "Our data suggests that despite the absence of slc11a1, its functions have been undertaken by one of the slc11a2 duplicated paralogs in teleost fish in a case of synfunctionalization, being involved in both iron metabolism and response to bacterial infection." (PMID 21501491, 2011).
infectious disease (23 papers, 2005 to 2025). A disorder directly resulting from the presence and activity of a microbial, viral, or parasitic agent in humans. "SLC11A1 (Nramp-1) is a strong candidate target for influencing autoimmune and infectious disease susceptibility." (PMID 36531992, 2022). "In cattle, SLC11A1 gene is mapped to chromosome 2 where the most well-studied polymorphism related to infectious disease resistance/susceptibility is a (GT)n microsatellite polymorphism, characterized by variations in the number of GT repeats." (PMID 34485444, 2021). "As a pro-inflammatory factor, SLC11A1 is closely related to the occurrence and development of many inflammatory diseases and susceptibility to infectious diseases." (PMID 34631695, 2021). "Earlier studies have shown that genetic factors can influence the innate immune response to mycobacterial antigens, such as infectious disease susceptibility genes, e.g., SLC11A1, HLA-DR, vitamin D3 receptor, and mannose binding protein." (PMID 27097163, 2016). "SLC11A1 has pleiotropic effects on macrophage function and remains a strong candidate for infectious disease susceptibility." (PMID 21599885, 2011). "Significant evidence suggests that a promoter polymorphism withinthe gene SLC11A1 is involved in susceptibility to both autoimmune and infectious disorders." (PMID 15757519, 2005). "However, while SLC11A1 has been linked genetically to multiple human autoimmune and infectious diseases, studies of its function have been limited primarily to restriction of intramacrophage pathogens." (PMID 38374245, 2024). "It has, therefore, been hypothesized that allele 3 would provide protection against infectious disease by driving high SLC11A1 expression and resulting in Th1-mediated immune response." (PMID 35242163, 2021). "SLC11A1 is implicated as a strong candidate for human susceptibility to tuberculosis, and has been associated with autoimmune and infectious disease in human conditions such as rheumatoid arthritis, multiple sclerosis, pulmonary tuberculosis, visceral leishmaniasis and meningococcal meningitis." (PMID 25874773, 2015). "The identification of variants associated with susceptibility/resistance to infectious diseases such as TB will be useful to further probe the relationship between (mainly) non-coding polymorphism at SLC11A1 locus and pathogenesis of infectious and/or immune diseases." (PMID 24832660, 2013). "SLC11A1 (Solute Carrier Family 11 Member 1) is involved in iron metabolism and the host’s resistance to certain infectious diseases." (PMID 39548146, 2024). "At present, Slc11a1 has not been characterised in many taxa, and despite its known roles in mediating the effects of infectious disease agents, has not been examined as a candidate gene in susceptibility or resistance in any wild population of conservation concern." (PMID 25874773, 2015).
cancer (18 papers, 2007 to 2025). A tumor composed of atypical neoplastic, often pleomorphic cells that invade other tissues. "Our results indicated that fibroblasts, cancer-associated fibroblasts (CAFs), and macrophages (M0, M1, and M2) infiltrated more in the high-SLC11A1 group." (PMID 36438826, 2022). "We also demonstrated that SLC11A1 is associated with poor prognosis in other common cancers of the digestive system, such as STAD, PAAD, and LIHC." (PMID 36438826, 2022). "We would use immunostaining to validate the relationship between SLC11A1 and immune cells, such as fibroblasts, cancer-associated fibroblasts (CAFs) and macrophages (M1 and M2)." (PMID 36438826, 2022). "Further, we aimed to determine whether SLC11A1 levels are associated with clinical outcomes in patients with different cancers." (PMID 36531992, 2022). "This is quite different from the mechanism by which SLC11A1 indirectly affects RCD through immunoregulation in other cancers." (PMID 41007849, 2025). "Our study examined the expression patterns of SLC11A1 and its immunological function across a range of cancers." (PMID 36531992, 2022). "SLC11A1 was significantly upregulated in several cancer tissues compared with normal tissues (all p < 0.05), and was downregulated in several other cancer tissues." (PMID 36531992, 2022). "Western blot demonstrated that ATG10, PRKCD, and SPP1 were highly expressed in cancer tissues, while IL18RAP and SLC11A1 expression in cancer tissues was lower." (PMID 34631695, 2021). "We also investigated the prognostic value of SLC11A1 using pan-cancer data from TCGA." (PMID 36438826, 2022). "The results of our present study were consistent with previous results, and further suggested that SLC11A1 was closely related to cancers and may be used as their prognosis biomarker." (PMID 34925447, 2021). "Among the previously found cancer-hallmark survival-related genes (PAK6, SLC11A1, SULT1A1 and TUBB6), we observed that their differential expression still had a significant impact on survival for three of the genes (PAK6, SLC11A1 and TUBB6), when considering stage stratification." (PMID 34885088, 2021). "However, several studies have demonstrated that SLC11A1 is also closely related to cancers." (PMID 34925447, 2021). "We show that SLC11A1 is expressed at low levels in tumor samples, and it has been suggested that transcriptional repression of SLC11A1 leads to cell proliferation and survival if unchecked, which could result in cancer and autoimmunity." (PMID 33193731, 2020). "The results showed that mRNA levels of ATG10, IL18RAP, PRKCD, SLC11A1, and SPP1 differed between tumor tissues and normal tissues in most of the 33 cancer types." (PMID 34631695, 2021). "According to the evidence displayed above, the role of SLC11A1 in EC is not a simple extension of its function in other cancers but has adapted to the unique pathological environment (hormonal microenvironment, unique treatment vulnerability) of EC." (PMID 41007849, 2025). "Furthermore, a subsequent analysis on the possible role of the altered genes in CRC and IPD data sets in the survival of cancer patients (TCGA-COAD data sets) pointed to a significant influence on survival for eight of these genes (TUBB6, PAK6, SULT1A1, SLC11A1, TRAP1, FAM50B, SPON2, FES)." (PMID 34885088, 2021). "Although SLC11A1 shows excellent immunological prognostic value in other cancers, our K-M curves show better survival for high-expression groups of GBP2, P2RX7, and HCLS1 but not SLC11A1 in EC." (PMID 41007849, 2025). "SLC11A1, TNFRSF1B, and LTBR have not yet been reported on prognostic factors in GBM, thus, suggestive of novel target candidates for cancer immunotherapy." (PMID 29721184, 2018).